ORAI1 (ORAI calcium release-activated calcium modulator 1)
Diseases named in the same sentence as ORAI1 in open-access papers (continued):
Sharing a sentence is not in itself a finding about the gene and the disease.
cancer (continued). "Interestingly, a correlation between STIM1 and Orai1 expression and specific cell cycle regulators has been found in most cancers, providing targeted therapeutic options." (PMID 36612099, 2022). "The apparent contradiction between the pro and anti-apoptotic effects of STIM/Orai-mediated SOCE could be explained in part by the fact that different cancer cell types have varying expression levels of Orai1 and STIM1." (PMID 35821821, 2022). "However, SOCE can be enhanced in cancer cells due to an increase in the expression and/or function of its underlying molecular components, i.e., STIM1 and Orai1." (PMID 35884372, 2022). "Thus, Orai1 exhibits diverse functions in cancers that reflect the spectrum of Ca2+-dependent behaviors of cancer cells." (PMID 36310590, 2022). "Thus, Orai1 plays key role in a Ca2+-dependent behavior of cancer cells, which will have to be elucidated further." (PMID 36310590, 2022). "Intriguingly, a partial inhibition of Orai1 might result in an increase of perforin-dependent cancer cell killing by cytotoxic T cells, fueling the hypothesis that partial inhibition of Orai1-dependent SOCE may contribute to tumor elimination." (PMID 34201758, 2021). "In oral/oropharyngeal squamous cells, Orai1 enhances cancer stemness by activation of NFAT pathway." (PMID 34012400, 2021). "SOCE inhibition through STIM1 or ORAI1 knockdown inhibits the proliferation and metastasis of cancer cells, suggesting that SOCE may act as an oncogenic pathway." (PMID 34122115, 2021). "Moreover, ORAI1-mediated SOCE is reported to play an important role in the progression of various cancers." (PMID 34055617, 2021). "STIM1 and ORAI1 have been reported to regulate invasion of cancer cells." (PMID 34155535, 2021). "In addition, studies on physiological roles of ORAI1 have mostly been performed in immune cells or in the (patho) physiological context of cancer." (PMID 34831241, 2021). "Interestingly, it has been demonstrated that SARAF and Orai1 work together to boost SOCE in highly proliferated cancers cells, MEG01 and NG115-401L, independently of STIM1." (PMID 33748129, 2021). "Interestingly, an essential trace mineral nutrient zinc is able to inhibit Orai1-mediated SOCE in ESCC cells, which has been linked to its cancer prevention function." (PMID 34012400, 2021). "Besides the homomeric Orai3 channel, additionally, ARC or LTC4 channels, both heteromeric assemblies of Orai1 and Orai3, have been reported to trigger the development of certain types of cancer cells." (PMID 34360783, 2021). "Specifically, Orai1 and TRPC6 channels are well established to be implicated in cell proliferation and migration and various hypertrophic gene expression is reported to be mediated by NFAT pathway activation in normal and cancer cells." (PMID 33916304, 2021). "In this part of the study, we investigated whether a potential interplay of SK3 and Orai1, as it occurs in specific cancer cell types, also applies to HEK 293 cells in the absence of STIM1." (PMID 34944977, 2021). "Moreover, STIM1 and Orai1 are upregulated in cancer cells and to trigger their development and growth." (PMID 33333945, 2020). "Moreover, inhibiting Stim1 and Orai1 results in the modulation of tumor migration, metastasis, and proliferation in other cancer cells." (PMID 32841278, 2020). "Contrarily, related cancer cells exhibit a co-expression of Orai1 and SK3 channels." (PMID 33333945, 2020). "The co-localization of SK3 and Orai1 in lipid raft domains reinforces cancer cell growth." (PMID 33333945, 2020). "ORAI1 is another protein involved in the regulation of Ca2+-mediated autophagy in cancer cells." (PMID 33171939, 2020). "Obviously, SPCA2 and SK3 possess analogue roles in the regulation of Orai1 in cancer cells." (PMID 33333945, 2020).
cancer (continued). "Our present findings showing that polyamine synthesis inhibition reverses remodeling of SOCs from TRPC1/Orai1 channels characteristic of cancer cells to the classic Orai1 channels reported in normal cells suggest that channel remodeling is critical to the tumorigenic pathway induced by polyamines." (PMID 30642111, 2019). "Thus, higher ROS levels in this case would be considered pro-tumorigenic, whereas in case the Orai3–Orai1 ratio is low and where mostly Orai1 homomultimers are formed, ROS levels would be considered anti-tumorigenic, resulting finally in cancer cell death." (PMID 30935064, 2019). "ORAI1 is overexpressed in different types of cancer including OSCC." (PMID 31040921, 2019). "Of note, Orai3 may replace Orai1 as the pore-forming subunit of store-operated channels in cancer cells and could, therefore, emerge as a promising target for anti-cancer therapies." (PMID 29324706, 2018). "Therefore, our study highlights the functional significance of Orai1 signaling in malignant progression of OSCC by enriching cancer stemness." (PMID 27259269, 2016). "Our study identifies Orai1 as a novel molecular determinant for OSCC progression by enhancing cancer stemness, suggesting that inhibition of Orai1 signaling may offer an effective therapeutic modality against OSCC." (PMID 27259269, 2016). "Since Orai1 is readily inhibited by small molecular inhibitor, targeting Orai1 signaling may be a plausible therapeutic modality against cancer." (PMID 27259269, 2016). "Moreover, precancerous oral epithelial cells express higher Orai1 protein than normal oral epithelial cells, suggesting that Orai1 plays an important role in cancer progression." (PMID 27259269, 2016). "Orai1 was overexpressed in various human cancers, including lung, esophagus, brain, and kidney." (PMID 27259269, 2016). "The observation of significant higher expression of STIM2 in ESCC cell lines than that in HET-1A cells implies that STIM2 may play an important role in regulation of Orai1 channel activity and overall intracellular Ca2+ signaling in this type of cancer." (PMID 24797725, 2014). "Reflecting the eminent importance of CRAC current following receptor stimulation, several recent studies addressed the role of Orai1/STIM1 in chemotactically or chemokinetically stimulated migration with a particular focus on cell adhesion both in cancer cells as well as in vascular endothelium." (PMID 24204345, 2013). "TRP/Orai1 functions in cancer and endothelial cell migration." (PMID 24204345, 2013). "Orai1 also associates with the small conductance Ca2+-activated K+ channel 3 (SK3) or the Golgi-resident secretory pathway Ca2+-ATPase 2 (SPCA2) to generate constitutive Ca2+ currents, which are important for proliferation, migration, and tumorigenesis of cancer cells." (PMID 39303919, 2024). "Additionally, it has been claimed that SOCE could play a role in the oncogenic pathway, since its blockage, which can be achieved through the knockdown of STIM1 or Orai1, prevents the proliferation and spread of cancer cells." (PMID 37259313, 2023). "Notably, Orai1 is a novel molecular regulator of tumorigenicity and stemness, thus targeting Orai1 signaling may be a plausible therapeutic modality against cancer and microgravity might be a new good perspective in GBM therapy." (PMID 35678198, 2022). "Therefore, it seems that the post-translational modifications of Stim1 and Orai1 play a role in (cancer) cell migration and polarized plasma membrane organization, as demonstrated by several groups through RNA interference, gene-knock-out, or Stim1 overexpression systems." (PMID 35254656, 2022). "However, although the involvement of the Orai1 channel in cell proliferation is well established, most of the research evidence has shown that Orai1 mediates the G2/S phase of the cell cycle, especially in cancer cells." (PMID 34063470, 2021). "Indeed, there is evidence for a co-regulation of SK3 and Orai1 in breast and colon cancer cells." (PMID 34944977, 2021).
cancer (continued). "Finally, in cancer, ORAI1 and SOCE are significantly dysregulated." (PMID 34831241, 2021). "Thus, we investigated the effects of STIM1 or ORAI1 knock-down on ML-1 cancer cell invasion." (PMID 34155535, 2021). "SIGR1 is overexpressed in cancer cells with high metastatic potential, where it can form a molecular complex with the small-conductance Ca2+-activated potassium (SKCa) channel and the Ca2+-release-activated Ca2+ modulator 1 (ORAI1), which favors cancer cells migration." (PMID 32927611, 2020). "In MDA-MB-231 cell lines, it has been reported that overexpression of Orai1, as well as calcium–calmodulin-activated adenylyl cyclase type 8 (which interacts at phosphorylation sites), prevents the inactivation of Orai1, increasing calcium signaling and promoting cancer cell migration." (PMID 33511135, 2020). "Considering the differences in redox-sensitivity between Orai1, Orai2, and Orai3, the ratio between the isoforms might be an interesting factor regulating Ca2+ signals under oxidative stress conditions during pathophysiological situations like cancer." (PMID 30935064, 2019). "However, a recent study demonstrated that partial inhibition of Orai1 might paradoxically increase perforin-dependent cancer cell killing of CTLs, leading to a hypothesis that partial inhibition of Orai1-dependent SOCE may contribute to tumor elimination." (PMID 31252656, 2019). "Furthermore, since SOCE mediators such as STIM1 and ORAI1 are elevated in cancer cells and contribute to cancer aggressiveness, the exacerbation of SOCE might constitute a mechanism of resistance against TKI therapies." (PMID 29662626, 2018). "In human prostate cancer cells, downregulation of Orai1 and decreased SOCE was correlated to an apoptosis-resistant phenotype, suggesting that loss of SOCE could contribute to the uncontrolled proliferation of cancer cells." (PMID 27417567, 2016). "In addition, STIM1 and ORAI1 inhibited NF-κB signaling and remodeled the tumor microenvironment by reducing the formation of M2 phenotype macrophages, possibly creating an unfavorable tumor microenvironment and inhibiting cancer development." (PMID 26257076, 2015). "It applauses the possibility that STIM2 may replace STIM1 to couple with Orai1 in cancer cells." (PMID 24797725, 2014). "Store-operated calcium entry (SOCE), mediated by ORAI1-3 calcium channels and stromal interaction molecules STIM1 and STIM2, is increasingly recognized as a regulator of cancer progression." (PMID 41801973, 2026). "Collectively, elevated expression of both ORAI1 and ORAI3 underpins cancer hallmarks across diverse tumor types, positioning them as prognostic indicators and actionable therapeutic targets in malignancies, including lung cancer." (PMID 41596760, 2026). "Store-operated calcium entry (SOCE), involving components such as STIM1, Orai1, and SARAF, plays a critical role in calcium signaling and cancer progression." (PMID 40362663, 2025). "SOCE is the major influx of Ca2+ in non-excitable cells, however, high expression of STIM1, ORAI1, and activated SOCE were found to be involved in cancer progression, migration, and metastasis for cervical cancer, breast cancer and hepatocarcinoma." (PMID 38903530, 2024). "Channels like ORAI1 and TRPV2 play roles in cancer cell invasion through the ECM and formation of invadopodia." (PMID 38510751, 2024). "The expression of STIM1 and ORAI1 was first evaluated in cytospins of spiked PC-3 and DU-145 cancer cells with PBMCs by immunofluorescence using antibodies against CK, STIM1, and ORAI1." (PMID 38903530, 2024). "There are many reports that Orai1 is involved in cell proliferation, migration, metastasis, apoptosis and epithelial–mesenchymal transition (EMT) in various cancers." (PMID 37759164, 2023). "However, whether EP4 also regulates Ca2+ through Orai1 in other cancers remains elusive." (PMID 37759164, 2023). "Therefore, Orai1 may be a novel potential target for the treatment of cancers." (PMID 37759164, 2023).
cancer (continued). "Our study further showed that the activation of Ca2+-dependent transcription factor, NFAT (nuclear factor of activated T cells) was required for Orai1-induced stemness promotion in OSCC, indicating the novel role of the Orai1/NFAT axis in cancer stemness." (PMID 37759448, 2023). "Another example for ion channel co-regulation in cholesterol-rich regions represents the interplay of Orai1 with the Ca2+ activated K+ ion channel, SK3, primarily in cancer cells." (PMID 35327543, 2022). "Emerging roles of Ca2+ in cancer stem cell (CSC) population maintenance and stemness have been reported, and some studies have proposed a link between ORAI1 and the regulation of the CSC compartment." (PMID 35628366, 2022). "In cancer cells, the SK3-Orai1 complex is located within cholesterol-rich regions, where it triggers a constitutive Ca2+ influx specific to Orai1." (PMID 36612099, 2022). "The expression of important markers of EMT and requisite regulators of mesenchymal cell migration, such as vimentin or fibronectin, is downregulated in esophageal and gastric cancer upon STIM1 and/or Orai1 silencing." (PMID 36612099, 2022). "Emphasis is placed on the structure/function relationship of the well-studied store-operated Ca2+ channel, i.e., Orai1, and the Ca2+-activated K+ channel, i.e., SK3, alongside their individual and joint roles in cancer." (PMID 36612099, 2022). "In line with the findings in cancer cells, we discovered a close co-localization of SK3 and Orai1, which is likely responsible for local enhancements in Ca2+ levels." (PMID 35327543, 2022). "This suggests, in agreement with previous findings in cancer cells, that the co-occurrence of Orai1 and SK3 increases cytosolic Ca2+ levels specifically through Orai1, which together with SK3 triggers the positive feedback mechanisms." (PMID 36612099, 2022). "Our data therefore show that in these two cancer models (i.e., AML and PDAC), the ORAI1 expression level is significantly higher than that in “normal” cells and is modified when cells are exposed to chemotherapy drugs." (PMID 35628366, 2022). "In agreement with previous reports on other cancer cell types, serum-evoked SOCE was dampened by blocking Orai1 channels with either Pyr6 (10 μM) or BTP-2 (20 μM) in MDA-MB-231 cells." (PMID 36231082, 2022). "There is significant interest in the literature in the role of SOCE in cancer progression and metastasis with implication on the role of STIM1 and Orai1 in cell migration." (PMID 34069353, 2021). "Regarding the STIM1/Orai1-mediated SOCE, further studies aiming at developing potent and selective inhibitors that target cancer cell-specific microtubule-dependent STIM1 trafficking mechanism on SOCE activation will facilitate better therapeutic approaches." (PMID 35008759, 2021). "In thyroid follicular ML-1 cancer cells, SOCE was significantly decreased in both stable STIM1 (STIM1-KD) and ORAI1 (ORAI1-KD) knock-down cells, compared with control mock-transfected cells." (PMID 34155535, 2021). "In these cancer models, σ1R forms a molecular platform with calcium-activated K+ channel SK3 and Orai1, which is responsible for increased Ca2+ entry that finally enhances cancer cell migration." (PMID 33842465, 2021). "Activation of the cAMP-PKA cascade was shown to lessen the activities of sole and Orai1-complexed SK3, hindering Ca2+ influx and in turn, mobility of cancer cells." (PMID 33466526, 2021). "Accumulating evidence has revealed that many cancers, such as breast, liver, lung, gastric, colon, and ovarian cancer, exhibit augmented SOCE and overexpression of STIM1 or ORAI1." (PMID 34122115, 2021). "In immune cells, it controls fundamental processes such as proliferation, cell adhesion, and migration, while in cancer, SOCE and ORAI1 gene expression are dysregulated and lead to abnormal migration and/or cell proliferation." (PMID 34831241, 2021).
cancer (continued). "Overall, there is evidence that SK3 and/or Orai1 are modulated via accessory proteins as well as lipids, either when heterologously expressed in HEK 293 cells or when endogenously occurring in cancer cells." (PMID 33333945, 2020). "In cancer cells, the major calcium influx pathway is through store-operated calcium channels, which are composed by STIM1 and Orai1." (PMID 33348924, 2020). "Moreover, Orai1 is capable of endowing non-tumorigenic immortalized oral epithelial cells with self-renovation, and concurrently enhances transcribing pluripotent and cancer stem cells-associated agents such as Nanog, Sox2, KLF4, Oct4, Zeb1, Bmi1, and Zeb2." (PMID 32280305, 2020). "Many pathophysiological cellular functions in aging and cancer involve SOCE and Orai3, highlighting the importance of understanding the pharmacology of Orai1/Orai3 heteromeric SOCE channels." (PMID 32252254, 2020). "In many cancer types including HCC, enhanced expression of STIM1 and Orai1 have been shown to enhance carcinogenesis including proliferation, migration and invasion processes." (PMID 31366337, 2019). "As knowledge on the importance of SOCE in tumor biology and cancer progression accumulates, the blockade of STIM1/Orai1-dependent Ca2+ signaling has emerged as the potential and plausible targets for cancer therapeutics." (PMID 31252656, 2019). "Aberrant overexpression of STIM1 or Orai1 and thus upregulated SOCE activity have been observed in several types of human cancers." (PMID 31252656, 2019). "Tumor expression of Orai1 and STIM1 have substantial implications for the adverse prognosis of cancer patients." (PMID 31252656, 2019). "In order to unravel the molecular underpinnings of constitutive Ca2+ entry, we undertook protein knockdown of Stim1, Orai1 and Orai3, that have been involved in SOCE activation in cancer cells, by using a siRNA silencing approach." (PMID 30123430, 2018). "In cancer cells, SK3 co-localizes with Orai1 in plasma membrane lipid rafts where the complex operates independently of STIM1 as a constitutive Ca2+ entry pathway." (PMID 30558192, 2018). "Specifically, the dysregulation of distinct molecular components of SOCE, especially the STIM1 and Orai1 proteins and their homologues STIM2, Orai2, and Orai3, plays important roles in the pathophysiology of different types of cancer." (PMID 29951353, 2017). "We further provided evidence that Orai1 promotes OSCC progression by enhancing cancer stemness via NFAT signaling, suggesting a novel CSC regulatory mechanism by Orai1/NFAT axis." (PMID 27259269, 2016). "The ORAI calcium release-activated calcium modulator 1 (ORAI1) was reported to be involved in cancer progression and metastasis of several types of cancers." (PMID 26380267, 2015). "Recent studies have demonstrated an important role for ORAI1 and STIM1 proteins in cancer cells and carcinogenesis." (PMID 23922331, 2013). "Knockdown of ORAI1 and STIM1 has also been shown to sensitize cancer cells to anti-cancer drugs." (PMID 38510751, 2024). "Further studies regarding the similarities and differences of Orai1 function in cancer cells and non-cancer cells." (PMID 37759164, 2023). "There are many reports that Orai1 is related to cell migration/metastasis and proliferation regardless of cancer type." (PMID 37759164, 2023). "Based on numerous previous studies, Orai channels (Orai1, Orai2 and Orai3 channels) control Ca2+ release-activated Ca2+ (CRAC) currents and contribute to SOCE currents in other types of cells, including various cancer cells." (PMID 37759164, 2023). "These types of cancer exhibit an augmented SOCE response and overexpression of STIM1 and/or Orai1." (PMID 36982380, 2023). "The targets include the Orai1-STIM complex because of its central role in Ca2+ influx, signaling, and T cell function, P2X7 and P2X4 channels, and KV1.3, KCa3.1 in the immunological fight against cancer." (PMID 37705981, 2023).